SYP (synaptophysin)
Diseases named in the same sentence as SYP in open-access papers (continued):
Sharing a sentence is not in itself a finding about the gene and the disease.
adrenal tumor (6 papers, 2014 to 2022). "A panel of markers (CD56, vimentin, melan-A, inhibin-α, synaptophysin, chromogranin and SF-1) are used to establish the origin of adrenal tumors." (PMID 34803919, 2021). "In primary adrenal tumor and gastric metastasis the tumor cells were marked by vimentin, inhibin, synaptophysin, neuron-specific enolase, and calretinin." (PMID 26376405, 2015). "Immunohistochemistry analysis of the adrenal tumor was strongly positive for CgA, synaptophysin and VIP." (PMID 25081061, 2014).
breast tumors (6 papers, 2013 to 2023). "Immunofluorescence of Neurofilament Light Chain (NF-L, neural fibers), Tyrosine Hydroxylase (TH, catecholamine nerves) and synaptophysin (SYP) confirm the presence of neural signals in both human and mouse breast tumors." (PMID 37463926, 2023). "Notably, proximity analyses between neural markers and nuclear phospho-CREB1/ATF1 indicate that higher cancer-cell CRE activity is present in the region proximal to neural signals (NF-L, TH and SYP positive area) in breast tumors." (PMID 37463926, 2023). "Sensitivity and specificity of currently used markers are limited; based on the definitions of WHO Classification of Tumours, 5th edition, about 50% of breast tumors with features of neuroendocrine differentiation express chromogranin-A and 16% express synaptophysin." (PMID 34764822, 2021). "We isolated human breast tumors that displayed NED based on their co‐expression of four NED markers SCG2, CHGB, CHGA, and synaptophysin, SYP." (PMID 35653631, 2022).
glioblastoma (6 papers, 2013 to 2025). The most malignant astrocytic tumor (WHO grade IV). "We speculate that the SYP gene may be involved in the decreased myelin function that occurs in glioblastoma development." (PMID 38724609, 2024). "In addition, a local expression of synaptophysin was observed in perivascular cells in case P2 and in recurrent glioblastoma P5." (PMID 29805974, 2018).
Intellectual disability (6 papers, 2014 to 2025). "We have previously implicated inefficient sybII retrieval in human disease, with intellectual-disability associated variants of synaptophysin all failing to rescue sybII retrieval in synaptophysin null cultures." (PMID 26871701, 2016). "Mutations in the iTRAP synaptophysin have been identified in individuals with familial forms of intellectual disability." (PMID 26903854, 2016). "In contrast, AAC2 treatment promoted the expression of inhibitory synaptic genes, Syn2 (synapsin II) and Syp (synaptophysin), examined in the context of vesicular trafficking of neurotransmitters, and mutation (T198I) is associated with epilepsy and intellectual disability." (PMID 39519239, 2024). "Importantly, each of the intellectual disability-associated variants of synaptophysin have a reduced ability to coordinate sybII retrieval during endocytosis, suggesting that is it specifically this process that is perturbed in individuals harboring mutations in synaptophysin." (PMID 26903854, 2016).
ischemic stroke (6 papers, 2021 to 2024). A stroke disorder caused by obstruction of blood flow to the brain, due to thrombotic (local blood clot formation) or embolic (due to a blood clot or other material traveling from another site) event. "According to the statistical analysis, the nicorandil treatment prevented the decrease in SYP levels caused by ischemic stroke, as this group presented higher SYP levels than the other two MCAO-operated groups." (PMID 33497397, 2021). "Higher SYP protein levels were detected in the Sham group, and ischemic stroke significantly decreased SYP levels." (PMID 33497397, 2021). "We found that 14 days after ischemic stroke, astrocytes and microglia/macrophages engulfed synaptic elements immunolabeled for both presynaptic (synaptophysin, SYP) and postsynaptic (Homer-1) proteins in the microgliosis and astrogliosis areas." (PMID 34836962, 2021). "The densities of SYP+ presynapse, PSD+ postsynapse and SYP+/PSD95+ synapse were increased in microglial and astroglial cKO mice after ischemic stroke, as compared with the control." (PMID 34836962, 2021). "We found that 14 days after ischemic stroke, MEGF10KO or MERTKKO in microglia/macrophages or astrocytes resulted in reduced engulfment of SYP+ and Homer-1+ synaptic puncta in microglia/macrophage or astrocytes compared with controls." (PMID 34836962, 2021). "They found that the cytoplasm of microglia/macrophages contained synaptic elements, including presynaptic (synaptophysin, SYP) and postsynaptic (Homer‐1) proteins, and that these cells engulfed both inhibitory and excitatory synapses in an MCAO model of ischemic stroke." (PMID 38727249, 2024).
mesenchymal tumors (6 papers, 2017 to 2025). "All the PIWIL2-GFP fibroblasts derived tumors tested stained positive for the transfected gene, PIWIL2, as well as VIMENTIN (marker of mesenchymal tumors), Synaptophysin (SYN, markers of neurogenic tumors) and NESTIN." (PMID 28103575, 2017). "Regarding Case 2, it is noteworthy that it labeled not only for synaptophysin but also for chromogranin-A, a combination that we encountered only rarely in mesenchymal neoplasms with neuroendocrine features (data not shown)." (PMID 34228212, 2022).
Obesity (6 papers, 2020 to 2024). Accumulation of substantial excess body fat. "The relationship between obesity and ORG is facilitated by a network of various inflammation-associated cells (e.g., synaptophysin) and a series of inflammatory mediators (e.g., TNF-α and IL-6)." (PMID 39234117, 2024). "Previous studies revealed that excessive dietary intake reduces the expression of synaptic markers, including presynaptic vesicle marker (SYP) and a postsynaptic density protein (PSD-95), in an animal model of obesity." (PMID 31963819, 2020). "Thus, we evaluated the effect of CAF on synaptophysin and BDNF as markers of neuroplasticity to further investigate the relationship between gut and brain in obesity." (PMID 36235574, 2022). "In contrast to the hippocampus, maternal obesity did not affect mRNA expression of EphA4, PSD-95 and synaptophysin in the PFC (p = 0.479; p = 0.329; p = 0.888; p = 0.535)." (PMID 38308309, 2024).
oligodendroglioma (6 papers, 2014 to 2025). A well-differentiated (WHO grade II), diffusely infiltrating neuroglial tumor, typically located in the cerebral hemispheres. "The expression pattern of synaptophysin differs significantly between oligodendrogliomas and diffuse midline gliomas, making it a useful diagnostic tool in neuropathology." (PMID 40937216, 2025). "The presence of synaptophysin positivity supports an oligodendroglioma diagnosis and is often associated with a more indolent course and better response to chemotherapy and radiotherapy." (PMID 40937216, 2025). "This narrative review utilizes a descriptive thematic approach to examine the diagnostic and prognostic utility of vimentin, synaptophysin, and H3K27me as surrogate immunohistochemical markers in differentiating oligodendrogliomas from diffuse midline gliomas (DMGs)." (PMID 40937216, 2025). "Synaptophysin, a neuronal differentiation marker, is often expressed in oligodendrogliomas due to their partial neuronal-like differentiation." (PMID 40937216, 2025). "In particular, vimentin, synaptophysin, and histone H3 lysine 27 methylation (H3K27me) have gained attention as potential surrogate markers that aid in differentiating oligodendroglioma from DMGs." (PMID 40937216, 2025). "Eligible literature included peer-reviewed articles focused on the diagnostic, histopathological, immunohistochemical, or molecular characterization of oligodendrogliomas and DMGs, with a specific emphasis on vimentin, synaptophysin, or H3K27me expression." (PMID 40937216, 2025). "Because synaptophysin is expressed in multiple tumor types, its positivity alone cannot confirm an oligodendroglioma diagnosis." (PMID 40937216, 2025). "The degree of synaptophysin expression can vary, but its presence supports the diagnosis of oligodendroglioma over astrocytic tumors." (PMID 40937216, 2025). "Immunohistochemically, synaptophysin staining in oligodendrogliomas is often focal or patchy, with cytoplasmic and perinuclear positivity." (PMID 40937216, 2025). "Oligodendrogliomas frequently exhibit synaptophysin positivity, supporting the notion that these tumors retain neuronal-like differentiation." (PMID 40937216, 2025). "In our cohort, tumors expressing canonical neuronal markers like neurofilament (NEFL, NEFM, and NEFH) and synaptophysin (SYP) were significantly localized within the expression space of oligodendrogliomas (q-value < 0.015)." (PMID 32732999, 2020). "Most DMGs exhibit absent or weak synaptophysin staining, a feature that helps differentiate them from oligodendrogliomas." (PMID 40937216, 2025). "Another limitation is the focal versus diffuse staining patterns as in oligodendrogliomas, synaptophysin expression is often focal rather than diffuse." (PMID 40937216, 2025). "In summary, synaptophysin is a useful immunohistochemical marker for identifying neuronal differentiation, with strong expression typically seen in oligodendrogliomas and absent or weak expression in DMGs." (PMID 40937216, 2025). "Synaptophysin, a neuronal differentiation marker, is frequently expressed in oligodendrogliomas but largely absent in DMGs, offering discriminatory value." (PMID 40937216, 2025). "Potential limitations of synaptophysin include variable expression in oligodendrogliomas because while most oligodendrogliomas are synaptophysin-positive, some may exhibit weak or absent staining." (PMID 40937216, 2025). "However, synaptophysin is not entirely specific to oligodendrogliomas and should always be interpreted in conjunction with other molecular and histological markers." (PMID 40937216, 2025). "As our case demonstrated cells exhibiting oligodendroglioma-like appearance, strong OLIG2 and synaptophysin expression, and absence of widespread GFAP expression, the diagnosis of DGONC was assigned based on these morphological features." (PMID 40475045, 2025).
oligodendroglioma (continued). "With findings of cells exhibiting oligodendroglioma-like appearance, strong OLIG2 and synaptophysin expression, and absence of widespread GFAP expression, the diagnosis was revised to DGONC." (PMID 40475045, 2025).
colorectal cancer (5 papers, 2013 to 2023). A primary or metastatic malignant neoplasm that affects the colon or rectum. "Synaptophysin (SYP) has also been found to play a role in a variety of diseases such as colorectal cancer, frontotemporal dementia syndrome and epithelioid hemangioendothelioma." (PMID 37041519, 2023). "Another recently studied CSC marker is the neuroedocrine marker synaptophysin, whose nuclear expression was observed in CSCs derived from lung and colorectal cancer, as we recently published." (PMID 35269569, 2022). "On the other hand, colorectal carcinoma with neuroendocrine differentiation is also a unique subtype of colorectal carcinomas showing expression of at least one distinctive marker among chromogranin A, synaptophysin, and CD56." (PMID 36434637, 2022).
insulinomas (5 papers, 2013 to 2025). "ASCL-1 also regulates the expression of NE markers such as NCAM1, insulinoma-synaptophysin (SYP), insulinoma associated protein 1 (INSM1), chromogranin A (CHGA), and CGRP." (PMID 39858036, 2025). "Histologically, insulinomas are epithelial neoplasms associated with strong and diffuse immunohistochemical expression of neuroendocrine markers such as synaptophysin and chromogranin." (PMID 26374700, 2015). "The diagnosis of LCNEC requires positive immunohistochemical staining with chromogranin A, synaptophysin, and CD56, along with a morphological diagnosis, and insulinoma-associated protein 1 (INSM1) has been proposed as an additional marker but is still not an ideal or better marker." (PMID 38067335, 2023). "Synaptophysin, a marker of neuroendocrine cells, was found to be generally expressed in both insulinomas and PDICs, indicating that these tumors still maintained aspects of neuroendocrine differentiation, however some PDICs exhibited heterogeneous downregulation." (PMID 23691228, 2013).
metastatic carcinoma (5 papers, 2014 to 2024). A carcinoma which has spread from the original site of growth to another anatomic site. "Immunohistochemically, primary and metastatic cancer cells were diffusely positive for chromogranin A and the estrogen receptor (Allred's total score: 8) and focally reactive for synaptophysin and the progesterone receptor (total score: 5)." (PMID 36572422, 2022). "Immunohistochemical staining is a valuable tool in diagnosing metastatic neuroendocrine carcinoma, as these tumors often express neuroendocrine markers such as chromogranin, synaptophysin, and CD56, which can aid in distinguishing them from other types of metastatic carcinoma." (PMID 39483593, 2024). "In the tumour finally diagnosed as metastatic carcinoma, immunodetection of CgA was negative and synaptophysin was detected small number of tumour cells only." (PMID 24695372, 2014).
pituitary adenoma (5 papers, 2011 to 2025). "Pathology was again consistent with pituitary adenoma with positive synaptophysin and adrenocorticotrophic hormone (ACTH) immunoreactivity (ACTH not shown)." (PMID 26425577, 2013). "Additional analysis of neuroendocrine markers showed that the tumors stained positive for the intermediate lobe pituitary marker beta-endorphin (B-END) and synaptophysin (SYN), which are commonly observed in pituitary adenomas." (PMID 22574128, 2012). "The neuropathologist who initially encountered the lesion had noted that it was negative for the immunostaining normally expected in a pituitary adenoma, such as chromogranin and synaptophysin." (PMID 31845864, 2020). "The tumor at this time no longer expressed synaptophysin or pankeratin AE1/AE3, markers of pituitary adenomas that had been present in the previous 2 tumors." (PMID 26425577, 2013).
primitive neuroectodermal tumor (5 papers, 2009 to 2025). A malignant neoplasm that originates in the neuroectoderm. "Immunohistochemistry showed diffuse strong membrane positivity for MIC2, focal positivity for synaptophysin and negativity for desmin and diagnosis came compatible with ES or primitive neuroectodermal tumor (PNET)." (PMID 25206203, 2013). "Primitive neuroectodermal tumor expresses neuronal marker such as synaptophysin, neurofilament protein, nonspecific enolase or S-100." (PMID 23198232, 2012).
schwannoma (5 papers, 2018 to 2025). A benign, usually encapsulated slow growing tumor composed of Schwann cells. "In our analysis, we observed that the markers SMA, Desmin, CD117, DOG-1, ALK, Synaptophysin, Chromogranin and AE1/AE3 stained negatively in all analyzed schwannomas." (PMID 30710876, 2019). "In the majority of cases, schwannoma, gastrointestinal stromal tumor, and leiomyoma can be easily distinguished using immunohistochemical staining (S-100 protein, c-Kit, CD34, synaptophysin, and chromogranin A)." (PMID 30101131, 2018).
Sepsis (5 papers, 2017 to 2025). Sepsis is defined as life-threatening organ dysfunction caused by a dysregulated host response to infection. "However, another study found a single i.p. injection of LPS induced synaptophysin loss lasted at least for 2 months after sepsis." (PMID 31354429, 2019). "To further confirm the selectivity of the loss of sepsis-induced NMDA receptor expression, we also detected the expression of the synaptic protein synaptophysin and the neuron number in the CA1." (PMID 29176858, 2017). "Recently, a decrease in synaptophysin and PSD95 expression was described following neuroinflammation induced by the cecal ligation and puncture (CLP) model of sepsis or after intraperitoneally administration of LPS—a component of Gram-negative bacteria." (PMID 33632243, 2021). "There were no significant changes in synaptophysin levels in any of the groups analyzed after the EE protocol in animals submitted to sepsis (sham + SE = 0.73 ± 0.11; sham + EE = 0.68 ± 0.14; CLP + SE = 0.68 ± 0.09; CLP + EE = 0.64 ± 0.08)." (PMID 35798809, 2022). "Similarly, we found that synaptophysin and PSD95 levels were lower in animals born from mothers with gestational sepsis." (PMID 33632243, 2021). "In this study, we found that sepsis decreased the levels of GluN2A, GluN2B andGluN1 but not synaptophysin in the hippocampus of mice during the late stage of sepsis." (PMID 29176858, 2017). "Sepsis selectively decreased the protein and mRNA levels of GluN2A, GluN2B and GluN1 but not the levels of synaptophysin or the neuronal number in the hippocampus of mice in either of the classic CLP-induced or LPS-induced sepsis models during the first 7 days after sepsis." (PMID 29176858, 2017). "There were no obvious changes in synaptophysin expression in the hippocampus or in the numbers of neuron in the CA1 of septic mice, which were detected in the two classic sepsis models." (PMID 29176858, 2017).
urothelial carcinoma (5 papers, 2009 to 2025). A malignant neoplasm derived from the transitional epithelium of the urinary tract (urinary bladder, ureter, urethra, or renal pelvis). "Stage IV high-grade urothelial carcinoma with small cell neuroendocrine differentiation of the ureter with regional lymph node metastases, confirmed by histopathology and immunohistochemistry (synaptophysin+, CD56+, Ki67 >75%)." (PMID 41257218, 2025). "The strong expression of three neuroendocrine markers (CD56, chromogranin and synaptophysin) and the absence of expression of two epithelial markers (CK7 and CK20), exclude the possibility of invasive urothelial carcinoma arising from the renal pelvis in the case herein presented." (PMID 19523243, 2009).
X-linked intellectual disability (5 papers, 2014 to 2021). An X-linked intellectual deficiency in which not enough information is known, reported or published to indicate whether a gene causes non-syndromic or syndromic presentations. "Among these genes, PLP2, CCDC22, and SYP mutations were associated with X-linked intellectual disability." (PMID 34659328, 2021). "Screening of known human synaptophysin mutations revealed a similar presynaptic phenotype between T198I and a mutation found in X-linked intellectual disability." (PMID 28887151, 2017). "A series of mutations in the SYP gene have been identified in patients with X-linked intellectual disability." (PMID 28887151, 2017). "Confirmation of a key role for synaptophysin in sybII retrieval came from analysis of a series of synaptophysin mutants identified in X-linked intellectual disability." (PMID 26903854, 2016). "Mutations in SYP lead to X-linked intellectual disability implicating its involvement in learning and memory." (PMID 26909693, 2016). "To determine whether this was a common consequence of synaptophysin dysfunction, we determined the effect of a series of synaptophysin mutations identified in patients with X-linked intellectual disability on sybII surface expression." (PMID 28887151, 2017).
adrenocortical adenoma (4 papers, 2016 to 2023). "With the goal of identifying the mechanism involved in dysregulation of SYP through methylation, three adrenocortical adenoma samples associated with CPA and their adjacent normal adrenal cortex tissues were chosen to identify the expression of miRNAs." (PMID 31352437, 2019). "To identify the expression of SYP in human adrenocortical adenoma, we performed the real time quantitative PCR, western blotting and immunohistochemical staining on 12 adrenocortical adenoma samples from CS and their adjacent normal adrenal cortex tissues." (PMID 31352437, 2019). "The immunohistochemical profile (alpha-inhibin+, Melan-A+, synaptophysin+) indicated the adrenocortical origin of the tumor, diagnosed as ectopic adrenocortical adenoma." (PMID 27094262, 2016). "Hence, it is possible that SYP may play an important role in adrenocortical adenoma tissues." (PMID 31352437, 2019).